IL6 (interleukin 6)
Diseases named in the same sentence as IL6 in open-access papers (continued):
Sharing a sentence is not in itself a finding about the gene and the disease.
periodontitis (continued). "Several blood cell components, including erythrocyte sedimentation rate (ESR), C-reactive protein (CRP), interleukin-6 (IL-6), fibrinogen, Von Willebrand factor, and thrombocytes, have been studied in connection with periodontitis." (PMID 38595889, 2024). "The presence of elevated salivary IL-6 in OSCC patients reinforces the notion of a periodontitis–oral cancer link." (PMID 38612423, 2024). "IL-6, IL-17, and IL-35 levels were significantly higher in the periodontitis group than in the healthy group (p < 0.001)." (PMID 39215253, 2024). "Compared to healthy controls, patients with periodontitis present with high levels of pro-inflammatory substances (IL-1, IL-6, CRP, fibrinogen) and an increased number of neutrophils in the blood." (PMID 39064809, 2024). "Results indicated that patients with periodontitis had significantly higher levels of IL-6, LDH, and CRP compared to the control group, highlighting an association between elevated biomarker levels and periodontitis." (PMID 38595889, 2024). "MMP-8, MMP-9, IL-1β, IL-6, and Hb have been effective salivary biomarkers for detecting periodontitis in systemically healthy individuals, while MMP-9 and IL-1β also perform well in identifying non-periodontitis conditions." (PMID 39554809, 2024). "We have focused on the cytokines IL-6 and IL-8 as being the key drivers of inflammatory processes in periodontitis." (PMID 39629237, 2024). "Our study noted that IL-6 concentrations are higher in the saliva of patients with periodontal disease, and these elevated levels are capable of detecting active periodontitis." (PMID 39917715, 2024). "The periodontitis group exhibited significantly higher levels of IL-6, IL-17, and IL-35 compared with the healthy group (p < 0.001)." (PMID 39215253, 2024). "Bone resorption phenomena are initiated by IL-6-mediated factors, and in the case of treatments applied to periodontitis patients, cytokine levels decrease." (PMID 38791469, 2024). "Arias‐Bujanda highlighted that the salivary biomarker Hb exhibits similar sensitivity (72%) to MMP8 and IL6 for diagnosing periodontitis, with even better specificity (75% compared to 70.5% and 73%, respectively)." (PMID 39554809, 2024). "The findings indicate that participants in group 2, diagnosed with periodontitis, displayed markedly higher mean IL-6 levels compared to those in the control group (group 1)." (PMID 38595889, 2024). "Overall, the study's findings suggest a significant rise in inflammatory markers such as IL-6 and IL-17 during the pathogenesis of periodontitis, indicating their strong involvement in the inflammatory process." (PMID 39215253, 2024). "Individuals with periodontitis exhibited higher levels of serum inflammatory markers, such as C-reactive protein (CRP) and interleukin-6 (IL-6), which are associated with an increased risk of cognitive impairment and AD." (PMID 39768299, 2024). "While interleukin-6 (IL-6) levels were significantly higher in the periodontitis group (p < 0.05), symmetric dimethylarginine (SDMA) concentrations were notably lower compared to the control subjects (p < 0.05)." (PMID 39329863, 2024). "Tacrolimus, a calcineurin inhibitor, has been demonstrated to protect against the inflammation-induced tissue and bone loss associated with periodontitis in experimental rats and oral diseases through a mechanism involving IL-1β, TNF-α, and IL-6." (PMID 37435641, 2024). "Dysregulated and persistent synthesis of IL-6 can initiate chronic inflammatory responses, thus favoring the development or disease progression of gingivitis and periodontitis in the oral cavity." (PMID 38794529, 2024). "Along with IL-6, other proinflammatory cytokines (IL-1, IL-8 or TNF-α) are also associated with osteoclast generation, leading to the development of periodontitis symptoms and/or associated diseases." (PMID 38791469, 2024).
periodontitis (continued). "Studies have reported increased local levels of pro-inflammatory cytokines, such as interleukin-1beta (IL-1beta), tumor necrosis factor (TNF), IL-6, IL-17, and IL-23, in patients with periodontitis." (PMID 39253090, 2024). "Intriguingly, similar cytokines play a role in periodontal disease and the inflammatory mucous membranes of airways.Both IL-5 and IL-6 were found to be increased in asthmatic patients and those suffering from periodontitis." (PMID 38352910, 2024). "IL-6 is mainly produced by locally activated immune cells in periodontitis, such as neutrophils and macrophages resident in periodontitis lesions which can produce IL-6 ex vivo after bacterial stimulation." (PMID 39253090, 2024). "A cascade of inflammatory proteins and enzymes is directly involved in periodontitis’ osteoclastogenesis, including proinflammatory cytokines such as IL-1β, IL-6, IL-11, IL-17, and TNF-α (point 6)." (PMID 38792574, 2024). "Elevated BMI, waist circumference, and body fat are strongly associated with increased risks of periodontitis, with inflammatory mediators such as TNF-α and IL-6 playing critical roles." (PMID 39796559, 2024). "It should be noted that IL-6 is a component of a complex cascade of many proinflammatory cytokines involved in the development of periodontitis." (PMID 39458264, 2024). "The presence of periodontitis and cancer has also been suggested to synergistically increase IL-6 levels in serum of affected patients." (PMID 39253090, 2024). "Periodontitis is thought to cause low-grade systemic inflammation due to the production and release of inflammatory markers, including TNF-α and IL-6, into the bloodstream, which negatively affect endothelial function." (PMID 39062000, 2024). "Patients with chronic periodontitis presented increased levels of IL-6 and tumor necrosis factor-alpha (TNF-α) in saliva, while elevated levels of IL-6 and TNF-a in this fluid were also associated with chronic infections and autoimmune disorders." (PMID 39795606, 2024). "In this study, the median (range) of IL-6 in saliva was significantly higher in vaccinated participants with periodontitis than in controls and increased with the severity of disease." (PMID 39917640, 2024). "One of these interleukins that plays a role in the pathophysiology of periodontitis is interleukin 6 (IL-6)." (PMID 39458264, 2024). "Patients with periodontitis show higher levels of pro-inflammatory cytokines such as IL-1, IL-6, TNF, IFN-γ, IL-17, oncostatin M and CRP, and fibrinogen, as well as an increased number of neutrophils compared to the healthy control group." (PMID 38892299, 2024). "Periodontitis results in elevated systemic levels of C- reactive protein, IL-1β, IL-6, IL-8, and TNF-α." (PMID 39917647, 2024). "Compared to healthy controls, patients with severe periodontitis and elevated levels of proinflammatory mediators, such as interleukin-1, interleukin-6, C-reactive protein, and fibrinogen, also had increased neutrophils count in the peripheral blood." (PMID 38968002, 2024). "This suggests a direct connection between the role of IL-6 in the progression and recession of periodontitis." (PMID 38396821, 2024). "By using these mechanisms IL-6 can activate numerous types of target cells in chronic periodontitis." (PMID 39253090, 2024). "Proteomic analysis has revealed that chronic periodontitis induces systemic inflammation characterized by elevated levels of pro-inflammatory cytokines such as interleukin-6 (IL-6) and C-reactive protein (CRP)." (PMID 38892299, 2024). "Consistently, we detected higher expression levels of TNF-α and IL-6 in periodontitis tissues and ELISA results showed higher concentration of TNF-α and IL-6 in serum." (PMID 38319542, 2024). "Patients with periodontitis have higher values of white blood cells, interleukin (IL)-1, IL-6, tumor necrosis factor (TNF)-α and C-reactive protein (CRP)." (PMID 38573898, 2024).
periodontitis (continued). "Another study indicated that human gingival fibroblasts (HGFs) contribute to periodontitis development by increasing IL-6 production, a response to pathogens and cytokines, and interacting with fibroblasts and macrophages through VEGF activation." (PMID 39822781, 2024). "From our data, we observed a classical pro-inflammatory profile with elevated levels of IL-1β and IL-6 in periodontitis patients." (PMID 39125970, 2024). "Several studies have demonstrated the proinflammatory role of interleukin (IL)-6 in the context of periodontitis." (PMID 39215253, 2024). "The application of EV therapy in periodontitis presents significant clinical opportunities by demonstrating how EVs can influence key cytokines like IL-5, IL-6, IL-17A, IL-10, and TNF-α." (PMID 38891939, 2024). "Beyond its role in periodontitis, IL-6 induces oral carcinogenesis by promoting the hypermethylation of tumor suppressor genes, such as CHFR, GATA5, and PAX6." (PMID 38612423, 2024). "Previous studies have shown increased IL-6 expression in saliva and gingival fluid in patients with periodontitis." (PMID 39458264, 2024). "Further studies need to be conducted to thoroughly understand the role of IL-6 in the pathogenesis of periodontitis, both chronic and aggressive." (PMID 38396821, 2024). "GF and periodontal ligament fibroblasts facilitate the inflammatory cascade in periodontitis, producing pro-inflammatory cytokines, like IL-1β, IL-6 and TNF-α." (PMID 39252697, 2024). "In addition to its effect on osteoclasts, studies have demonstrated that IL-6 has a connection to the release and activation of metalloproteinases, which may cause pathological extracellular matrix breakdown in periodontitis patients whose IL-6 serum levels are higher than normal." (PMID 39274511, 2024). "This study revealed upregulated levels of IL-6, IL-17, and IL-35 in periodontitis patients compared to healthy individuals." (PMID 39215253, 2024). "IL-6, a cytokine known to induce acute phase responses, was also found at higher levels among periodontitis cases in this study." (PMID 39101637, 2024). "Massive cytokine production during chronic inflammation contributes to the interaction of periodontitis and diabetes, with common factors including IL-1β, IL-6, prostaglandin E2 (PGE2), TNF-α production." (PMID 39193343, 2024). "The role of IL-6 has been demonstrated in several diseases, including periodontitis, where it contributes to the development of chondral inflammation, periodontal ligament damage and destruction of bone support." (PMID 38791469, 2024). "Biopsy specimens of gingival tissue in which IL-6 expression was detected were taken from 14 patients with periodontitis and 8 controls who had undergone minor surgery." (PMID 39458264, 2024). "Regarding mDCs, we observed that the frequency of IL-6-producing mDCs and IL-6 expression by mDCs (after stimulus) was lower when compared to the moderate periodontitis group (p = 0.003 and p = 0.036, respectively)." (PMID 39274511, 2024). "In humans, IL-6 levels in gingival crevicular fluid levels were significantly higher in subjects diagnosed with chronic periodontitis as compared to periodontally healthy control subjects." (PMID 39253090, 2024). "The GCF IL-6, IL-17, and IL-35 levels were significantly higher in periodontitis subgroups than in the healthy group (p < 0.001)." (PMID 39215253, 2024). "IL-6 is known to play a role in pathogenesis or periodontitis via the induction of osteoclast differentiation to facilitate bone resorption as well as the inhibition of bone formation." (PMID 39851590, 2024). "A previous study also observed that diseased and healthy periodontal tissues, from a group of periodontitis patients compared to periodontally healthy subjects, had similar levels of IL-6 transcription and protein." (PMID 37882908, 2024).
periodontitis (continued). "In detail, M1 macrophages mainly take part in the destructive process of periodontitis by evoking secretion of diverse pro-inflammatory factors, such as interleukin-6 (IL-6), tumor necrosis factor-α (TNF-α) and inducible nitric oxide synthase (iNOS)." (PMID 38689292, 2024). "The transcription levels of soluble ACE2 and IL-6 were higher in periodontitis participants than in control participants, but within periodontitis groups, only IL-6 expression was higher in G2 than in G1." (PMID 39917640, 2024). "Patients with severe periodontitis had higher blood neutrophil counts and pro-inflammatory mediator levels (such as IL-1, IL-6, CRP, and fibrinogen) compared to healthy controls, which were associated with a higher cardiovascular risk." (PMID 38877442, 2024). "Fábio Vidal and colleagues found that periodontitis therapy reduces plasma levels of Interleukin-6, C-Reactive Protein, and fibrinogen in patients with severe periodontitis and refractory arterial hypertension." (PMID 39298393, 2024). "Another study demonstrated that periodontitis leads to increased serum levels of IL-6 and expansion of regulatory T cells in patients with cancer." (PMID 39253090, 2024). "Treatment of periodontitis effected IL-6, LDL, HDL, TC, TG and SBP with moderate certainty of evidence while the certainty of evidence on CRP, IL-1β, TNF-α, DBP and FMD was low." (PMID 38877442, 2024). "In this study, IL-6 levels were significantly lower in patients with periodontitis after NSPT compared to the control group." (PMID 38877442, 2024). "Proinflammatory cytokines, such as IL-6, are involved in the pathogenesis and progression of periodontitis." (PMID 38541692, 2024). "Our results showed high salivary levels of IL-6 and total proteins in periodontitis patients (p < 0.001), with detection ability reflected by an Area Under the Receiver Operating Characteristic Curve (AUC-ROC) ranging between 0.709 and 0.852." (PMID 39917715, 2024). "In a recent intervention study in PD, application of photodynamic therapy resulted in significant improvement in the clinical parameters of periodontitis and immunological biomarkers IL-6 and TNF-α in PD patients with severe periodontitis." (PMID 38674088, 2024). "A meta-analysis demonstrated that periodontitis treatment improves atherosclerosis by performing an analysis of inflammatory biomarkers (IL-6, IL-1β, sVCAM-1, sE-selectin, etc.)." (PMID 39298393, 2024). "In particular, patients with chronic periodontitis have elevated levels of proinflammatory cytokines, including IL-6, in the gingival crevicular fluid and serum compared to healthy controls." (PMID 37767526, 2023). "Compared to individuals with a healthy periodontium, patients with periodontitis show elevated levels of IL-6." (PMID 37568161, 2023). "Individuals with periodontitis have elevated circulatory levels of pro-inflammatory cytokines, such as IL-1, IL-6, and TNF-alpha." (PMID 38029267, 2023). "IL-6 and HsCRP levels were higher in the moderate–severe chronic periodontitis group than in the mild periodontitis group." (PMID 37239434, 2023). "Second, as a chronic inflammatory condition, periodontitis can also secrete IL-6 and proinflammatory factors as from adipose tissue, which can increase CRP levels." (PMID 37481511, 2023). "Regarding the TGF-β concentration, we observed a decrease in patients with moderate risk, as well as an increased concentration of IL-6 and hs-CRP in periodontitis patients." (PMID 36860987, 2023). "High levels of pro-inflammatory cytokines such as TNFα, IL-6, IL-1, and IL-17 are present in the milieu of both periodontitis and SSc." (PMID 36899985, 2023). "Given these conflicting reports, further research is required to clarify the role of IL-6 in periodontitis." (PMID 36840029, 2023).
periodontitis (continued). "Obese subjects with periodontitis are characterized by an increase in pro-inflammatory cytokines (IL-1β, IL-6, TNF), also in blood, and also in gingival fluid samples, compared to normo-weighted subjects with periodontitis." (PMID 37894804, 2023). "IL-6 and CRP are involved in insulin resistance, and now these inflammatory factors are thought to be the cause of the adverse effect of periodontitis on glycemic control." (PMID 36904268, 2023). "The pro-inflammatory cytokines TNF-α and IL-6 were increased in the APDC-KO mice after 3 weeks of periodontitis induction, whereas the pleiotropic cytokine IL-2, which mediates both pro- and anti-inflammatory functions, was significantly decreased." (PMID 37928259, 2023). "IL-1 and IL-6 play key roles in the early phase of periodontitis and are detected at high levels in periodontal lesions." (PMID 37367059, 2023). "Both periodontitis and colon cancer have been associated with elevated MDSC levels, and increased levels of TNF-α, IL-1β, IL-6 and MMP-9 are also common factors in both conditions." (PMID 38029267, 2023). "Interleukin 6 (IL-6) is considered to play a role in the dysbiotic host response in the development of periodontitis." (PMID 37342352, 2023). "In periodontitis, various proinflammatory cytokines such as IL‐1β, IL‐6, and tumor necrosis factor‐α (TNF‐α) are produced." (PMID 37506160, 2023). "Periodontitis is a prevalent chronic disease that triggers the production of proinflammatory cytokines such as IL-6, IL-8, and IL-1β as a response to bacterial infection." (PMID 39697803, 2023). "Periodontitis triggers a systemic inflammatory response mediated by various factors, including C-reactive protein, interleukin 1b (IL-1b), interleukin 6 (IL-6), tumor necrosis factor alpha (TNF-α), and others." (PMID 38001437, 2023). "Inflammatory mediators, such as C-reactive protein and IL-6, are also elevated in the serum of periodontitis patients." (PMID 36873050, 2023). "We found that IL-6 levels had a significant effect on CRP levels in periodontitis patients with CAD (path coefficient 0.322, p = 0.003)." (PMID 37239434, 2023). "In mice with periodontitis, the increased Th17-related genes (i.e.,Il6,Il17a, andRorγt), and Treg-related genes (i.e.,Foxp3,Il2,Il10,Ctla4,Cd25, andGitr) were detected in cervical lymph nodes and spleen." (PMID 37226540, 2023). "This study is the first study to analyze the effects of IL-6 -572 C/G, CRP -757 A/G, and CRP -717 T/C gene polymorphisms; IL-6 levels; and CRP levels on the severity of periodontitis in CAD, especially in the Indonesian population." (PMID 37239434, 2023). "The combination of NK357 with NK391 (NKc) additively decreased PG 16S rDNA levels and suppressed PG-induced periodontitis: the combination suppressed IL-6 and TNF-α expression and GP+LPS+ and NF-κB+CD11c+ cell populations in the periodontal tissue." (PMID 36904068, 2023). "Our meta-analysis demonstrated that IL-6 is a biomarker with a significant presence in the saliva of patients with periodontitis." (PMID 37026605, 2023). "Chronic periodontitis promotes the release of protein C-reactive protein, interleukin-1b and interleukin-6, and Tumor Necrosis Factor-alpha by neutrophils, which stimulate bone resorption and consequent destruction of periodontal tissue." (PMID 37297629, 2023). "Statistical analyses showed that nitric oxide, IL-6, IL-1B and osteoprotegerin are substances that are significantly present in patients with periodontitis (P < 0.05)." (PMID 37026605, 2023). "On the other hand, periodontal therapy has been shown to reduce plasma levels of interleukin-6, C-reactive protein, and fibrinogen in patients with severe periodontitis and refractory arterial hypertension." (PMID 37509588, 2023). "After periodontitis, IL-34 promotes monocyte development toward macrophages, and macrophages secrete a series of cytokines, such as IL-6 and TNF-α, mediating the inflammatory response." (PMID 36879647, 2023).